MMP9 (matrix metallopeptidase 9)
Diseases named in the same sentence as MMP9 in open-access papers (continued):
Sharing a sentence is not in itself a finding about the gene and the disease.
tumor (continued). "MMP-2 and MMP-9 are expressed in cancer cells that degrade the extracellular matrix (ECM) type IV collagen during tumor metastasis and invasion." (PMID 35355732, 2022). "Administration of bevacizumab causes the dose-dependent accumulation of collagen, MMP-2, and MMP-9, which play important roles in the adhesion process of tumor cell invasion and degradation of the cellular matrix." (PMID 35204054, 2022). "SIRT6 increases extracellular signal-regulated kinase (p-ERK) 1/2 phosphorylation and activates matrix metalloproteinase 9 (MMP9) to facilitate tumor cell migration and invasion." (PMID 35463332, 2022). "Survival analysis was performed using Xena UCSC, retrieving the log-rank test values and p-values calculated for the CG probesets related to LCN2, SLC22A17, and MMP9 in each tumor type." (PMID 36211450, 2022). "GBM cells produced soluble factors via PLOD2, which subsequently induced neutrophils to acquire a pro-tumor phenotype characterized by prolonged survival and the release of MMP9." (PMID 35682709, 2022). "They potentially facilitate tumor progression by the release of NE, cathepsin G, and MMP9, as well as tumor metastasis." (PMID 36031601, 2022). "Immunohistochemical analysis of MMP9 expression in tumor tissues revealed that invasion of the tumor was inhibited by SOL." (PMID 36506573, 2022). "Gpr35ΔMΦ tumours contained substantially less MMP2 and MMP9 compared with AOM/DSS-induced tumours from Gpr35fl/fl mice." (PMID 33758004, 2022). "On this basis, we conducted an in silico study to evaluate the role of LCN2, SLC22A17, and MMP9 genes and related isoforms in different tumor types by following specific workflow steps." (PMID 36211450, 2022). "In agreement with the in vitro findings, SB3 overexpression in MONSB3+ and SPH‐derived tumours was associated with an increase in NOTCH, MMP9 and the CSC‐related marker CD44 expression, at the protein level." (PMID 34478594, 2022). "In oral squamous cell carcinoma, TGF-β1 facilitates MT1-MMP-mediated MMP-9 activation and stimulates invasion of the tumor in collaboration with MT1-MMP and MMP-2." (PMID 35204054, 2022). "For instance, recent studies have reported an NP based on MMP-9-cleavable lipopeptide to control tumor proliferation and enhance drug accumulation in the tumor site." (PMID 36297426, 2022). "One of the sources of TGF-β, which has the function of inhibiting tumor cell differentiation, is the inactive precursor after proteolysis of MMP-9." (PMID 36080397, 2022). "In particular, MMP-9, a member of the gelatinase family, is one of the most complex action-performing MMPs, as it plays a key role in cancer cell invasion, tumor metastasis, and triggering the “angiogenic switch” (Bronisz and Kurkowska-Jastrzębska, 2016)." (PMID 35463960, 2022). "HB-derived exosomal lncRNA NEAT1 induced BMSCs differentiation into tumor-supporting myofibroblasts via modulating miR-132/MMP9 axis, which provided a new target for HB treatment." (PMID 35300348, 2022). "We first examined the expression of MMP2 and MMP9 in G401 cells and mouse tumour-bearing tissues after intervention with DCH." (PMID 36408277, 2022). "We found that endothelial-specific molecule 1 expression elevated bevacizumab-resistant tumor cells, and endothelial-specific molecule 1 further regulates MMP9, VEGF, and DLL4 to promote metastasis and angiogenesis in vitro and in vivo." (PMID 36428773, 2022). "Increased expression of MMP (MMP1, MMP2, MMP9, etc.)in the lesion induces the growth of tumor tissue and initiates its invasion and metastasis." (PMID 36293492, 2022). "Our study demonstrated that macrophages facilitate proliferation, migration, invasion, and tube formation in TECs by secreting VEGFA and MMP9, confirming the promoting effect of TAMs on tumor angiogenesis." (PMID 35436935, 2022). "The pro-angiogenic and tumour-growth-promoting role of MMP9 is well established and it has been correlated with poor survival." (PMID 35216069, 2022).
tumor (continued). "TNF-α-induced tumor initiation and tumor promotion are mediated by MMP-9-induced activation of NF-κB and AP-1-dependent signals in tumor cells." (PMID 35840633, 2022). "A large number of studies have confirmed that MMP9 is usually upregulated in tumor cells and is an inhibitor of tumor cell apoptosis, while caspase-3 is a proapoptotic factor." (PMID 36164442, 2022). "In both models, isoliensinine showed reduced tumor growth through the apoptosis of tumor cells mediated by increased caspase-3 activity, decreased levels of Bcl-2, Bcl-xL, and MMP-9, and decreased NF-κB p65 phosphorylation." (PMID 35158798, 2022). "Immunohistochemistry staining was also performed on tumor samples, and the results showed that there were fewer Ki-67- and MMP-9-positive cells in tumors that were treated with betulinic acid compared to the control." (PMID 35805049, 2022). "DLL4/Notch/Heyl/matrix metalloproteinase (MMP)-9 cascades promote the distant metastasis of the tumor, and lentivirus short hairpin RNA (shRNA) specifically silenced DLL4 in mice, which significantly inhibited the growth of transplanted tumors." (PMID 35096263, 2022). "In contrast, N2 neutrophils can release a large number of immunoregulatory factors, such as arginase and matrix metalloproteinase 9 (MMP-9) to promote tumor development." (PMID 36613779, 2022). "GBM cells triggered TLR2/6 stimulation in both macrophages and microglia via the myeloid differentiation primary response 88/TLR8 signaling pathway, which in turn results in the augmentation of MMP-9 which accelerate tumor invasion as well as angiogenesis." (PMID 35419058, 2022). "Recent studies have reported that HGF promotes the invasion of tumor cells associated with the up-regulation of MMP-2 and MMP-9." (PMID 36291760, 2022). "Some proteins, such as IL22, CCL20, and MMP9, all shown to be involved in tumor progression were exclusively higher in serum from rats with MLL-tumors." (PMID 35551231, 2022). "Two mechanisms were behind this tumour suppression: the reduction of MMP-9 and VEGF serum levels in mice, which means that tumour metastasis and angiogenesis were blocked." (PMID 36678733, 2022). "Since neutrophils do not produce TIMP-1 or gelatinase A, in contrast with monocytes and tumor cells, they are known to be a main source of MMP-9 for biochemical and biological studies." (PMID 35273488, 2022). "qRT-PCR analysis of genes implicated in angiogenesis process demonstrated that angiogenic factors, VEGF, IL8, TGFβ, and MMP9 were increased in the B cells co-cultured with HMGB1-overexpressing tumor cells as compared to control cells." (PMID 34617194, 2022). "Prodigiosin inhibited matrix metalloproteinase-9 (MMP-9) that is argued to release VEGF to regulate TAM-driven tumour growth and angiogenesis." (PMID 36577970, 2022). "HMGA1 has been found to associate with tumor invasion in several cancers, which was also observed in HCC based on its significantly positive correlation with MMP9 (PCC > 0.6)." (PMID 36132143, 2022). "In contrast, N2 neutrophils promote tumor growth by inhibiting natural killer cell function and releasing matrix metalloproteinase 9 (MMP9), which stimulates angiogenesis and dissemination of cancer cells." (PMID 35498537, 2022). "Within 24 h of A. Paniculata exposure, they saw a substantial decrease in mRNA expression of TM4SF3 and MMP9 in a concentration-dependent manner, inhibition of expression of HER2, CXCR4, MMP2, and MMP9, and depreciating tumor nodules." (PMID 35682652, 2022). "In human glioblastoma cells, it has been shown to induce MMP-CD44 shedding and tumor cell migration, and has also been reported to colocalize with MMP-9 in LRs, which plays a significant role in tumor invasion." (PMID 35207103, 2022). "These MMP-9 s generated by tumor-infiltrating neutrophils regulate tumor cell invasion and tumor angiogenesis at the same time." (PMID 36419156, 2022).
tumor (continued). "Further studies demonstrated that CQF significantly reduced IL-17A levels, which in turn inhibited NF-κB/IL-6/STAT3 signaling cascade, suppressed MMP9 expression and promoted tumor cell apoptosis." (PMID 35991881, 2022). "MMP-2 and MMP-9 are recognized as major contributors to the proteolytic degradation of extracellular matrix during tumor invasion." (PMID 35953439, 2022). "MMP9 regulates growth factors, cytokines, and chemokines and promotes an immune suppressive tumor microenvironment via matrix remodeling, tumor infiltration of T cells, and recruitment and activation of myeloid-derived suppressor cells." (PMID 35773363, 2022). "Liposomal SNAs efficiently co-delivered DOX and CpG into tumors and released the two drugs upon biological stimuli of MMP-9 enzyme in tumor microenvironment (TME) and high concentration of endogenous glutathione in tumor cells." (PMID 35303868, 2022). "The results indicated that GNP prevents tumor metastasis effectively and is an effective inhibitor of MMP-9." (PMID 35954126, 2022). "Tumor cells precultured on the stiff substrate had the highest extravasation rate probably due to the elevated MMP9 expression in tumor cells." (PMID 36439519, 2022). "DHW-208 also significantly inhibited the expression of the tumor metastasis marker MMP9 in Hep3B and Bel7402 cells in a concentration-dependent manner." (PMID 35903690, 2022). "Reduce tumor growth and inhibited the activation of NF-κB pathway and expression of their proteins (cyclin D1, COX-2, MMP (mitochondrial membrane potential)-2, MMP-9, and Bc1-xL) that involve in proliferation, metastasis, and anti-apoptosis of tumor cells." (PMID 36670910, 2022). "Taken together, these results suggest that the largest amount of MMP9, which seems to be involved in resistance to bevacizumab, is expressed by the tumor-infiltrating neutrophils." (PMID 34980260, 2022). "In all tumor cells, levels of pro MMP-9 and pro MMP-2 remained unchanged following treatment with either CXCL12 or CXCL11 alone (100 ng/ml, 24 h) or in combination." (PMID 36539774, 2022). "Activated MMP-9 can degrade basement membrane (BM) type IV collagen to promote the invasion and migration of tumor cells." (PMID 35220878, 2022). "MMP9 plays an important role in tumor extracellular matrix remodeling and communication between tumor cells." (PMID 35299895, 2022). "Exosomes liberated from the tumor are able to transfer CD44 protein into mesothelial cells stimulating metalloproteinase-9 (MMP-9) expression, which supports cell homing and invasion." (PMID 35269636, 2022). "Of note, Kdm3a is a histone demethylase to regulate the availability of chromatin, while Lrp5 is a co-receptor of Wnt signaling and MMP9 is a matrix metalloproteinase to promote tumor migration." (PMID 35547745, 2022). "Analysis of patient tissue samples (n=22) revealed that in GBM, miR-181a-5p is strongly downregulated compared to ADAM8 and MMP9 mRNA expression, even in localized tumor areas." (PMID 35371977, 2022). "MMP9 controls VEGF release from tumour and neighbouring cells in the metastatic niche, so its decline would mitigate the angiogenic switch." (PMID 35106125, 2022). "Matrix metalloproteinase 2 (MMP2) and Matrix metalloproteinase 9 (MMP9) are important for tumor cell proliferation." (PMID 35672776, 2022). "To identify the underlying mechanism of tumor growth inhibition, we further investigated the alteration of tumor-progression-related protein expression, including MCL-1, XIAP, MMP-9, and VEGF after AITC treatment by IHC staining of tumor tissues." (PMID 36142326, 2022). "The MMPs, MMP-2, and MMP-9 are the most related to tumor metastasis and invasion, because they have gelatinases activity and can degrade the extracellular matrix." (PMID 35711540, 2022). "Matrix metalloproteinases (MMP2 and MMP9) not only release growth factors to promote the growth of tumor cells, but also promote cell shedding to facilitate the invasion and metastasis of tumor cells." (PMID 35668940, 2022).
tumor (continued). "We demonstrated that HOXD11 is a novel therapeutic target mediated by miR-138-5p promoting tumor metastasis of PSCC via the FN1/MMP2/MMP9 molecular pathway." (PMID 36151071, 2022). "We observed that the majority of the ER+ high miR-18a-expressing samples expressed MMP9, and these tumor specimens also expressed a higher CD4/CD8 and a higher CD206/CD68." (PMID 35626709, 2022). "Further, the rapid tumor growth in OPM-BMG xenografts was associated with an increase in the expression of pro-angiogenesis factors like VEGF and MMP-9, suggestive of stimulated neovascularization that appears to be driven by the increased ROS generation." (PMID 36591481, 2022). "In the local cohort, we showed that preoperative MMP9 plasma levels decreased after tumor resection and were correlated with tumor levels of MMP9 mRNA (p = 0.03)." (PMID 34980260, 2022). "CCL2 mediates tumor cell metastasis by binding to CCR2 on tumor cells and induces the expression of matrix metalloproteinase-9 (MMP-9) to increase the invasiveness of tumor cells." (PMID 35320940, 2022). "The expression of MMP9 and cyclin D1 was also suppressed in anti‐Chi3L1 antibody‐treated lung metastasis tumor tissues." (PMID 34861103, 2022). "Scientific evidence revealed that several proteases as MMP2 and MMP9 are involved in many steps of cancer, including primary tumor growth, angiogenesis, invasion of the basement membrane and stroma, and metastatic process." (PMID 36430394, 2022). "Human thyroid carcinoma tissue has also been reported to express MMP-1, MMP-2, and MMP-9 and these MMPs were localized in tumor cells and/or in the fibroblasts adjacent to or close to the invading tumor cells." (PMID 36551933, 2022). "In clinical samples, lncRNA NEAT1 and MMP9 expressions were elevated in tumor tissues, while miR-132 expression was decreased." (PMID 35300348, 2022). "Pharmacological and knockout-mouse approaches indicate that targeting MMP-9 and its upstream signaling pathways should yield useful therapeutic targets for brain injury, tumor, and CNS inflammatory disorders." (PMID 35740292, 2022). "As a key member of the zinc-dependent endopeptidase family, MMP9 has been widely considered to be involved in tumor cell proliferation and invasion." (PMID 36384455, 2022). "Specimens from 41 patients with T-cell non-HL having lymphoid hyperplasia were investigated and showed elevated levels of CCR7 and MMP-9 correlating with increased numbers of cancerous lesions and higher tumor stage." (PMID 35203305, 2022). "The half-life of andecaliximab is 1 week; therefore, it can inhibit tumor growth as an anti-MMP9 agent." (PMID 34992093, 2022). "A significant association between tumor aggressiveness and increased MMP-2 and MMP-9 levels has been proved." (PMID 36079127, 2022). "MMP12 and MMP9 were related to cancer development, progression, and survival through various pathological processes and play essential roles in tumor invasion and metastasis." (PMID 35741697, 2022). "As a result, various MMP-9 synthetic inhibitors have been developed and used in clinical trials to prevent tumor metastasis, but the results have been unsatisfactory because of high toxicity and the lack of specificity." (PMID 35463960, 2022). "Taken together, we provide evidence for a functional axis involving ADAM8/miR-181a-5p/MAPK/MMP9 in GBM tumor cells." (PMID 35371977, 2022). "The degradation of ECM, led by MMP-9, speeds up the angiogenic process, essential for tumor mass growth, by promoting the release of downstream angiogenic factors in the tumor microenvironment, such as VEGF." (PMID 36290354, 2022). "TANs actively contribute to tumor proliferation, angiogenesis, tumor progression, and metastasis through the high-level expression of neutrophil elastase and matrix metalloproteinase 9 (MMP9)." (PMID 36303138, 2022). "High MMP-9 expression levels corresponded to development of extra-thyroid invasion (p = 0.019), T status (p = 0.003), and depth of tumor infiltration (p = 0.019)." (PMID 36010303, 2022).
tumor (continued). "The efficacy of GS-5745-based MMP9 inhibition, either as a monotherapy or in combination with chemotherapy, remains to be tested in other tumours." (PMID 35158891, 2022). "Differential expression of MMP-9 in cancer and normal tissues was observed in all cancers, with MMP-9 being overexpressed in tumor tissue across cancer types." (PMID 35178444, 2022). "The objective of our study was to examine the expression of tumor-progression-associated MMPs (MMP-1, MMP-2, and MMP-9) and tissue inhibitors of metalloproteinases (TIMP-1 and TIMP-2) in locally invasive PTC and their relation to clinicopathological features." (PMID 36551933, 2022). "Recent studies have demonstrated that FN1 activates matrix metalloproteinase 2 (MMP2) and MMP9 expression to hydrolyze components of the basement membrane and thus can promote tumor invasion and metastasis in various cancers." (PMID 36151071, 2022). "The confirmation of these results in a larger cohort is mandatory as well as preclinical exploration of the mechanistical implication of tumor-infiltrating neutrophils in MMP9 expression and bevacizumab sensibility." (PMID 34980260, 2022). "The inhibition of Stat3, by type I IFN signaling, impairs VEGF and MMP-9 production by neutrophils and suppresses tumor angiogenesis." (PMID 35158807, 2022). "MMP-9 is also related to angiogenesis by regulating the deposition of tumor angiogenesis factors and proangiogenic factors, resulting in the recruitment of vascular endothelial cells." (PMID 36247874, 2022). "In contrast, the highly expressed MMP-9 in CAC inhibits the tumor by affecting the Notch signaling pathway." (PMID 36776395, 2022). "Supplementing conjugated linoleic acid decreased the levels of TNF-α, IL-1β, hsCRP, MMP-2 and MMP-9, which are biomarkers of tumor aggression and angiogenesis." (PMID 36776395, 2022). "Recent studies have confirmed that TAMs can secret pro-angiogenic factors such as VEGFA and MMP9 and thereby promote tumor angiogenesis." (PMID 35436935, 2022). "IHC assay presented that the expression of Ki67, MMP2 and MMP9 was strikingly lower in sh-circ-CSNK1G1-administered tumor tissues relative to sh-NC, suggesting the growth of tumor tissues was suppressed by sh-circ-CSNK1G1." (PMID 36109751, 2022). "MMP9 is an inducible MMP expressed heterogeneously by tumor epithelia, macrophages, neutrophils, other inflammatory cells, fibroblastic stroma, and tumor-associated endothelial cells." (PMID 34992093, 2022). "Much evidence depicts that intense MMP-9 and IL-1β staining were observed in M2-like macrophages and tumor cells at the invasive prostate zone." (PMID 36117852, 2022). "The latest research claims that lncRNA-PVT1 as a tumor gene participates in tumor development by regulating matrix metalloproteinase MMP9." (PMID 36164442, 2022). "On the other hand, once TGF-β1 is activated, it enhances the expression and synthesis of MMP9 by the Snail signaling pathway, thereby creating a positive autocrine regulatory loop modulation of tumor progression." (PMID 35406619, 2022). "Among them, MMP-2 and MMP-9 are the major proteinases contributing to extracellular matrix degradation in the process of tumor cell migration." (PMID 35468097, 2022). "Elevated levels of MMP9 are frequently observed in various types of cancers and are commonly considered to promote tumor growth and metastasis." (PMID 35406619, 2022). "In our study, we also demonstrated that ADAM15 regulated the migration and invasion of tumours by affecting MMP9." (PMID 35597804, 2022). "Crucially, MT1-MMP and MMP9 activity can release extracellular heparin-bound VEGF which can induce MMP2 and MMP9 expression from tumour cells, likely via VEGFR2 activation." (PMID 36045675, 2022). "Evidence from past literature demonstrates that SPHK1 enhances the production of MMP-2 and MMP-9 and thereby promotes tumor proliferation and invasion of colon cancer." (PMID 36309544, 2022).